TLR4 (toll like receptor 4)
Diseases named in the same sentence as TLR4 in open-access papers (continued):
Sharing a sentence is not in itself a finding about the gene and the disease.
Hepatic steatosis (continued). "This helps reduce the LPS leakage and suppress the expression of TLR4/NF-κB pathway in the liver, thereby improving lipid metabolism disorders, and alleviating hepatic steatosis." (PMID 38004120, 2023). "Inhibition of TLR4 has been shown to reduce tumour burden in mouse models of hepatic steatosis and colorectal metastasis." (PMID 36936437, 2023). "Unexpectedly, TLR4-expressing myeloid cells played a minimal role in regulating alcohol-induced fatty liver disease and adipose tissue inflammation." (PMID 36979389, 2023). "It is worth noting that metformin attenuates ischemia-reperfusion (IR) injury in fatty liver disease via the toll-like receptor 4 (TLR4)/NF-κB axis." (PMID 37492564, 2023). "Global TLR4 knockout mice have been reported to protect against alcohol-induced fatty liver disease." (PMID 36979389, 2023). "In previous reports, hepatic overexpression of SAA1 aggravated fatty liver inflammation by promoting intrahepatic platelet aggregation, while, recently, SAA1 was shown to exacerbate hepatic steatosis via the TLR4-mediated NF-κB signaling pathway." (PMID 36423130, 2022). "Liver-specific TLR4-nulled mice exhibited strong resistance to high-fat diet-induced liver injury and hepatic steatosis." (PMID 35355867, 2022). "A study found that propionate alleviated the ethanol-induced hepatic steatosis and enhanced hepatic function through maintaining the intestinal epithelial barrier function and inhibiting hepatic toll-like receptor 4 (TLR4)-NF-κB pathway." (PMID 36140990, 2022). "Activation of the TLR4 by LPS or TLR-9 by DNA derived from intestinal bacteria promotes steatohepatitis, while suppression of the TLR4 or TLR-9 attenuates liver steatosis, inflammation, and fibrosis in a few of mouse models of NASH." (PMID 36032141, 2022). "Conversely, mice harboring inactivating mutations in TLR4 or TNF- α receptor I (TNFRI) are protected against alcohol-mediated gut barrier disruption, hepatic steatosis, and progression ALD." (PMID 33815111, 2021). "In another study using a mouse model, probiotics treatment protected against the fructose-induced liver steatosis by attenuating Toll-like receptor 4 (TLR4) signaling in the liver." (PMID 34680522, 2021). "For example, rodents deficient in TLR4 and myeloid-differentiation factor-2 (MD2) are protected from methionine- and choline-deficient diet-induced liver inflammation and liver steatosis." (PMID 35053205, 2021). "In relation to NAFLD-related inflammation, previous studies in young mice have reported that short-term exercise training decreases the expression of proinflammatory genes (Tlr4, Tnfα, Mcp1), macrophage infiltration, and ameliorates fatty liver." (PMID 33546405, 2021). "The microenvironment of fatty liver disease upregulates TLR4 expression, increases intestinal permeability, and leads to a significant increase in serum LPS." (PMID 34956171, 2021). "Evidence reveals that fructose can promote the progression of fatty liver disease by regulating lipase activity, increasing intestinal permeability and motility via TLR4 on KCs and enhancing the interaction with thioredoxin-interacting protein in macrophages." (PMID 34956171, 2021). "Subsequent experiments focused on the effects of MGIG intervention on the levels of proteins of the TLR4/NF‐κB/Nlrp3 signalling pathway in HFD‐induced hepatic steatosis." (PMID 32410294, 2020). "In conclusion, PPE supplementation can ameliorate hepatic steatosis and inflammation by regulating lipid metabolism and modulating oxidative stress and the hepatic TLR4–MyD88 pathway in ALD induced by chronic ethanol exposure." (PMID 33353102, 2020). "Our current work demonstrated a novel mechanism of curcumin in preventing HFD-induced hepatic steatosis, i.e. to reduced gut-derived endotoxin translocation and hepatic TLR4/MyD88/NF-κB signaling pathway." (PMID 31788011, 2019).
Hepatic steatosis (continued). "Intestinal permeability, hepatic steatosis and mRNA and protein expressions of TLR4-related inflammatory signaling molecule were analyzed." (PMID 31788011, 2019). "Endotoxin LPS derived from intestine functions as a natural ligand of TLR4 and is closely related with hepatic steatosis and the development of NAFLD, we thus examined that the impact of curcumin on circulating LPS levels." (PMID 31788011, 2019). "Activation of autophagy by rapamycin attenuated EtOH-LPS-induced liver steatosis and injury by reducing TLR4/MD2 expression and interaction in macrophages." (PMID 28839246, 2017). "Hepatic steatosis and inflammation are significantly ameliorated in TLR4-mutant mice compared with TLR4-WT mice." (PMID 28353649, 2017). "Attenuating the ischemia/reperfusion injury in alcoholic fatty liver by suppressing of myeloid differentiation factor 88 and TLR4 protein expressions and the nuclear translocation of NF-kB after reperfusion." (PMID 26633388, 2015). "TLR4-mutant mice fed with a fructose-enriched diet had significantly less hepatic steatosis, MyD88, and TNFα level in comparison to fructose-fed wild type mice, supporting the role of endotoxins/TLR4 signaling in fructose-induced NAFLD." (PMID 25353664, 2014). "Toll-like receptor 4 (TLR4) is closely associated with hepatic steatosis and non-alcoholic fatty liver disease (NAFLD)." (PMID 41226211, 2025). "Additionally, curcumin played a role in preventing HFD-induced hepatic steatosis by enhancing the intestinal barrier function and modulating the TLR4/NF-κB hepatic inflammatory pathways." (PMID 38313314, 2024). "Likewise, Wagnerberger and colleagues found that L. casei supplementation improved hepatic steatosis and normalized hepatic TLR4 expression in fructose-fed mice." (PMID 39200311, 2024). "IL-17 and TLR4 determine hepatic steatosis, inflammation, and finally fibrosis." (PMID 39335657, 2024). "Chronic TLR4 activation exacerbates hepatic steatosis and fibrosis, and in advanced stages, may even contribute to hepatocarcinogenesis." (PMID 39796579, 2024). "Previous studies provided evidence that liver steatosis induced by HFD is associated with the increased localization of LPS within hepatic cells and the upregulation of TLR4, the receptor of LPS, suggesting a potential cause–effect relationship between LPS and liver inflammation." (PMID 38891768, 2024). "Moreover, MPGI was able to ameliorate hepatic steatosis and inflammation by modifying gut microbiota homeostasis, metabolites, and the TLR4/NF-κB and AMPK signaling pathways." (PMID 38069009, 2023). "Several studies have demonstrated that quercetin can restore gut microbiota imbalances and activate the Toll-like receptor 4 (TLR-4) pathway, thereby reducing inflammatory responses, and decreasing hepatic steatosis caused by the accumulation of hepatic triglycerides." (PMID 37570615, 2023). "Interestingly, reactivation of TLR4 in hepatocytes and in the whole body similarly promoted the development of hepatic steatosis in mice after chronic alcohol feeding." (PMID 36979389, 2023). "Interestingly, global TLR4 knockout mice (Tlr4LoxTB) were resistant to alcohol overconsumption-induced hepatic steatosis." (PMID 36979389, 2023). "Existing studies have reported that abnormally translocated LPS from enteric pathogens binds to TLR4 and activates the transcription factor NF-κB, which is responsible for inflammatory cytokine synthesis, ultimately leading to liver injury and hepatic steatosis." (PMID 36771448, 2023). "Hence, hub genes were enriched in TLR4-mediated inflammation, a process that generally contributes to fatty liver disease and regulates proinflammatory cytokines expression." (PMID 38049817, 2023). "In addition, the cell-type-specific role of TLR4 in alcohol-induced fatty liver disease has been reported." (PMID 36979389, 2023). "Additionally, the mucosal TLR4-induced MYD88 signaling pathway contributes to the development of hepatic steatosis." (PMID 33656663, 2021).
Hepatic steatosis (continued). "However, the study by Tao showed that adipocyte-specific TLR4 deletion in mice significantly increased the severity of HFD-induced hepatic steatosis while improving systemic insulin sensitivity." (PMID 34943809, 2021). "In this study, our aim is to investigate whether AS-IV can improve HFD-induced hepatic steatosis by inhibiting the expression of TLR4, MyD88, and NF-κB in the liver tissue of NAFLD rats." (PMID 33708118, 2020). "Our data suggest that hepatic TLR4 could be a crucial target to modulate energy homeostasis in hepatic steatosis." (PMID 32410294, 2020). "Our results reveal the potent effects of MGIG on lipid metabolism and suggest that hepatic TLR4 might be a crucial therapeutic target to regulate energy homeostasis in hepatic steatosis." (PMID 32410294, 2020). "Activation of TLR4 induces liver injury and fibrosis by triggering the production of various pro-inflammatory cytokines; mice lacking hepatocyte TLR4 exhibit improved glucose intolerance, insulin sensitivity, and hepatic steatosis." (PMID 32182914, 2020). "TLR4 is involved in the pathogenesis of fructose-induced, high-fat and high-cholesterol diet-induced, or methionine- and choline-deficient (MCD) diet-induced hepatic steatosis in mice." (PMID 32849904, 2020). "Therefore, the preventive effect of curcumin on hepatic steatosis is mediated, at least in part, by inhibiting hepatic TLR4-MyD88/NF-κB pathway and the subsequent production of TNF-α and IL-1β." (PMID 31788011, 2019). "Moreover, several experimental data suggest an interaction between LPS/TLR4 and hepatic lipid accumulation and that inactivation of TLR4 attenuates hepatic steatosis." (PMID 31163617, 2019). "Klebsiella pneumoniae is a highly adaptive, endotoxin-producing bacterium, and previous studies have implicated it in gut barrier dysfunction, systemic endotoxemia, and activation of the TLR4/NF-κB inflammatory cascade, which may contribute to hepatic steatosis, fibrosis, and metabolic dysfunction." (PMID 40756562, 2025). "Co-expression of Fzd9 and Wnt3a with TLR4 in neuronal or glial cells as a response to inflammatory stimuli supports the idea that TLR4 trafficking in ordered membrane domains might also be controlled by Wnt signaling in fatty liver diseases." (PMID 34832073, 2021). "Our findings demonstrated that metformin attenuated ischemia/reperfusion injury in fatty liver disease via the TLR4/NF-κB axis, suggesting that metformin could have potential therapeutic applications in ischemia/reperfusion injury associated with liver transplantation." (PMID 32270948, 2020). "However, whether curcumin can prevents high-fat diet-induced fat accumulation and hepatic steatosis by inhibiting TLR4 signaling is still unknown." (PMID 31788011, 2019). "By inhibiting the TLR4/NF-κB pathway and activating the Nrf2 pathway, EGCG enhances the intestinal barrier function and attenuates hepatic steatosis and inflammatory responses." (PMID 39858534, 2025). "As a result, FPB ameliorated hepatic steatosis and hepatitis symptoms by activating AMPK/SREBPs pathway and inhibiting the TLR-4/NF-κB pathway." (PMID 39947694, 2025). "GPs, derived from Gynostemma pentaphyllum, alleviate hepatic steatosis and gut barrier damage in HFD-induced NAFLD models by activating the AMPK and TLR4/NF-κB pathways." (PMID 39858534, 2025). "FPB protected ethanol-induced apoptosis, fatty liver, and hepatic inflammation through p-AMP-activated protein kinase and TLR-4/NF-κB signaling pathways." (PMID 38111317, 2024). "HOPE alleviated the inflammatory response in fatty liver IRI by inhibiting TFPI2 expression, which mainly involves regulating the TLR4/NF-κB inflammatory signaling pathways." (PMID 39617791, 2024). "This acute-phase response protein is known to trigger hepatic steatosis and intrahepatic inflammatory response by forming a SAA1/TLR4/NF-kappaB/SAA1 feedforward regulatory circuit, reported to facilitate MAFLD progression." (PMID 39595946, 2024).
Hepatic steatosis (continued). "SAA1 triggered hepatic steatosis and regulated inflammatory response by forming a SAA1/TLR4/NF-κB feedforward, which leads to NAFLD progression." (PMID 37007016, 2023). "As an important innate immune pattern recognition receptor (PRR), toll-like receptor 4 (TLR4) has been found to be upregulated in both NAFLD patients and animal models and is counted for the progression of hepatic steatosis, inflammation, and fibrosis." (PMID 35769208, 2022). "P. notoginseng saponins mediate the gut-liver axis to improve hepatic steatosis and fibrosis in NAFLD mice via a TLR4-dependent manner." (PMID 36212891, 2022). "Lactobacillus paracasei has been found to reduce the expression of TLR-4, CCL2, and TNF-α and improve liver steatosis." (PMID 35053205, 2021). "Our mechanistic studies in HFD-induced NAFLD mice potentially implied that PNS supplementation improved hepatic steatosis and fibrosis via inhibition of hepatic CD14 and TLR4 activation." (PMID 33656663, 2021). "The abundance of free fatty acids (FFAs) in the microenvironment of fatty liver disease activates inflammatory signaling pathways in KCs in a TLR2- and TLR4-dependent manner." (PMID 34956171, 2021). "In conclusion, QHF can significantly alleviate hepatic steatosis and inflammation in NASH mice by upregulating SOCS1 to inhibit the TLR4/NF-κB signaling pathway." (PMID 33293985, 2020). "Mechanistic studies found that herbal formula such as shenling baizhu powder alleviated hepatic steatosis and repaired colon mucosa via decreasing the expression level of endotoxin and inflammatory mediators (TNF-α, IL-1β) via the TLR4 pathway." (PMID 32477116, 2020). "After specific down-regulation of TLR4 expression in the hypothalamic ARC, we found the hepatic steatosis was partially reversed, which along with restoration of the expression of glucose and lipid metabolism-related genes." (PMID 28785099, 2017). "For example, acetate and propionate have been shown to reduce the hepatic gene and protein expression of lipogenic enzymes, thereby preventing liver steatosis, while butyrate attenuated the progression of MASLD by inhibiting Toll-like receptor 4 (Tlr4) mRNA and iNOS expression." (PMID 41373976, 2025). "Previous studies reported that OLE improved liver steatosis and downregulated hepatic TLR4, but the role of the LPS-TLR4 axis was not investigated." (PMID 38891768, 2024). "This occurs by means of the portal inflow of TLR-4 and TLR-9 agonists in mice, leading to heightened hepatic tumor necrosis factor alpha (TNF-α) expression and inflammation, a phenomenon particularly pronounced in mouse models of hepatic steatosis." (PMID 38613058, 2024). "Here, we report that MPGI can effectively improve the hepatic steatosis and liver functions of high-fat diet (HFD)-fed mice by regulating multiple pathways, including gut microbiota homeostasis and the LPS/TLR4/NF-κB, AMPK/ACC/CPT1A, and AMPK/ULK1/LC3B signaling pathways." (PMID 38069009, 2023). "TLR4 is a natural receptor of LPS and LPS-induced activation of TLR4 leads to NF-KB nuclear translocation, promotes the release of proinflammatory factors such as IL-6 and TNF-α, and induces the progression from simple fatty liver disease to NASH." (PMID 36860985, 2023). "Further studies are still needed to clarify how TLR4 regulates SIRT1 in hepatocytes and whether Cim supplementation could alleviate high-fat diet-induced hepatic steatosis and liver injury." (PMID 35355867, 2022). "Also, EtOH-treated mice had marked increases in hepatic steatosis, liver injury, and expression of pro-inflammatory mediators, including TNF-α, and TLR4-positive macrophages, Kupffer cells, and hepatocytes in the intestines and liver, respectively." (PMID 33815111, 2021).
Hepatic steatosis (continued). "Therefore, this study aimed to establish a rat model of fatty liver disease and explore the effect of HOPE on TLR4-mediated inflammatory responses during fatty liver IRI and its mechanism of action, thereby providing new intervention targets for treating IRI during fatty liver transplantation." (PMID 39617791, 2024). "Thus, our data suggested that MFG-E8 knockout promoted hepatic steatosis, inflammation, and fibrosis in MCD-induced NASH, which might be by activation of TLR4/NF-κB signaling pathway." (PMID 35769208, 2022). "Also, allicin could alleviate alcohol-induced hepatic steatosis in C57BL/6 mice by modifying gut dysbiosis and then reducing the production of lipopolysaccharide (LPS) and further inhibiting TLR4-mediated inflammation." (PMID 33728021, 2021). "Considering that TLR4 is expressed in multiple types of cells, an important question concerning NAFLD pathogenesis is whether and how the TLR4 in different cell types contributes to the development and progression of hepatic steatosis and inflammation." (PMID 34943809, 2021). "However, in our study, the pharmacological inhibition of TLR4 using eritoran did not improve systemic insulin resistance and hepatic steatosis in the FFD-fed mice." (PMID 34205789, 2021). "Consistently, excessive lipid accumulation could further promote TLR4/NF‐κB signaling to trigger the leakage of proinflammatory cytokines (TNF‐α, IL‐6, IL‐1β, and IL‐18), thus exacerbating the vicious cycle of inflammatory responses in the liver to aggravate fatty liver progression." (PMID 40501499, 2025). "Similar with TLR4, the mRNA level of TLR9 was significantly upregulated in patients with NASH, but not in patients with hepatic steatosis." (PMID 37020586, 2023). "In addition, absence of TLR4 downstream molecules IKKε and TBK1, or treatment with an IKKε- and TBK1-specific inhibitors showed a protective effect against hepatic steatosis." (PMID 37020586, 2023).